DRD3 (dopamine receptor D3)
Description:
Dopamine receptor that is primarily expressed in limbic areas of the brain and is involved in the modulation of cognitive, emotional, and endocrine functions. Plays a key role in regulating neuronal signaling pathways associated with motivation, reward, and behavior. Coupled to G(i)/G(o) proteins; activation leads to inhibition of adenylate cyclase and decreased intracellular cAMP levels. Involved in the control of locomotor activity and implicated in several neuropsychiatric disorders, including schizophrenia and substance use disorders. Promotes cell proliferation through MAP kinase signaling. Also involved in autophagy regulation: receptor activation stimulates AMPK, which phosphorylates RPTOR and enhances its interaction with MTOR, thereby inhibiting MTORC1 signaling and its downstream target RPS6KB1. This leads to activation of ULK1 and initiation of the autophagy cascade. Forms heterotetramers with DRD1 to potentiate beta-arrestin recruitment and mediate locomotor activity (By similarity).
Synonyms: D3DR; ETM1; FET1
Tractability: Small molecule: an approved drug acts on it; a structure with a bound ligand is known; a high-quality ligand is known; it has a binding pocket of medium quality; it belongs to a druggable protein family. Antibody: UniProt places it where antibodies can reach, with high confidence; its Gene Ontology location is reachable by antibodies, with high confidence; UniProt predicts a signal peptide or a membrane-spanning region. PROTAC: a small molecule that binds it is known. Other modalities: an approved drug acts on it.
Target class: Small molecule receptor (family A GPCR); Dopamine receptor; Family A G protein-coupled receptor; Monoamine receptor; Membrane receptor
Chemical probes: CHEMBL158627, CHEMBL244946, NGB2904 (high quality), PD081179
Safety:
Unwanted effects reported when the protein is acted on. In parentheses: how it was acted on, where the effect was seen, and who reports it.
Facilitate reward reinforcement (activation; central nervous system; source: Brennan et al. (2024))
insomnia (inhibition; central nervous system; source: Brennan et al. (2024))
nausea (inhibition; source: Brennan et al. (2024))
role in facilitating drug addiction/dependence (activation; central nervous system; source: Brennan et al. (2024))
Severe akathisia (inhibition; central nervous system; source: Brennan et al. (2024))
adverse events (source: ClinPGx)
cognitive impairment (source: ClinPGx)
extrapyramidal symptoms (source: ClinPGx)
opioid dependence (source: ClinPGx)
Gene: Protein-coding gene on chromosome 3 (114,127,580 to 114,199,407, reverse strand). Ensembl gene ENSG00000151577.
Subcellular location: Cell membrane
Pathways (Reactome):
Signal Transduction: Dopamine receptors; G alpha (i) signalling events
Gene Ontology:
Molecular function: dopamine neurotransmitter receptor activity, coupled via Gi/Go; protein binding; G protein-coupled receptor activity; dopamine neurotransmitter receptor activity
Biological process: adenylate cyclase-activating dopamine receptor signaling pathway; adenylate cyclase-inhibiting dopamine receptor signaling pathway; arachidonate secretion; behavioral response to cocaine; G protein-coupled receptor internalization; G protein-coupled receptor signaling pathway; intracellular calcium ion homeostasis; negative regulation of protein secretion; positive regulation of cytokinesis; prepulse inhibition; response to cocaine; response to histamine; acid secretion; circadian regulation of gene expression; dopamine metabolic process; learning; learning or memory; locomotory behavior; musculoskeletal movement, spinal reflex action; negative regulation of blood pressure; negative regulation of cytosolic calcium ion concentration; negative regulation of oligodendrocyte differentiation; negative regulation of phosphatidylinositol 3-kinase/protein kinase B signal transduction; negative regulation of synaptic transmission, glutamatergic; phospholipase C-activating dopamine receptor signaling pathway; and 14 more
Cellular component: plasma membrane; membrane; synapse
Genetic constraint (gnomAD): Loss-of-function variants: 12 observed, 32.2 expected, observed/expected ratio (o/e) 0.37, 90% interval 0.24 to 0.6. The upper end of that interval is the gene's LOEUF score, 0.6, which puts it in group 2 of 6, group 1 being the genes least tolerant of losing a copy. Missense variants: 408 observed, 472.75 expected, observed/expected ratio (o/e) 0.86, 90% interval 0.8 to 0.94. Synonymous variants: 173 observed, 191.24 expected, observed/expected ratio (o/e) 0.9, 90% interval 0.8 to 1.03.
Homologues: Orthologues: chimpanzee DRD3 (99% identical), macaque DRD3 (98% identical), dog DRD3 (94% identical), rabbit DRD3 (92% identical), pig DRD3 (91% identical), mouse Drd3 (90% identical), rat Drd3 (89% identical), guinea pig DRD3 (70% identical), zebrafish drd3 (62% identical). Paralogues in human: DRD4 (37% identical), HTR1A (30% identical), HTR1D (29% identical), DRD5 (28% identical), HTR4 (28% identical), DRD1 (27% identical), HRH2 (27% identical), CHRM4 (26% identical), HRH3 (26% identical), HRH1 (25% identical), CHRM1 (24% identical), CHRM2 (24% identical), and 13 more.
Diseases named in the same sentence as DRD3 in open-access papers:
DRD3 is named in the same sentence as 92 diseases in open-access papers, as found by Europe PMC text mining. Sharing a sentence is not in itself a finding about the gene and the disease. The quoted sentences say what the papers report.
schizophrenia (53 papers, 2006 to 2025). A major psychotic disorder characterized by abnormalities in the perception or expression of reality. "In contrast, DRD3 gene hypermethylation is associated with decreased expression, and dysregulated methylation of COMT and DRD3 genes is linked to both schizophrenia risk and sex-specific differences." (PMID 39678047, 2024). "These keywords indicate that the green cluster has publications that focus on BDNF polymorphism associated with smoking/nicotine in schizophrenia as well as functional polymorphisms of other genes such as dopamine, drd3 and COMT." (PMID 37077958, 2023). "The association with schizophrenia was found for DRD3 rs6280 (p = 0.05) and HTR2A rs7322347 (p = 0.0013)." (PMID 34025476, 2021). "The results of the significantly preferential transmission of DRD3 Ser9 allele in East Asian group showed that the serine allele appears to be protective against schizophrenia." (PMID 32316934, 2020). "Actually, the genetic heterogeneity will complicate the etiology of schizophrenia because the allele distributions of DRD3 Ser9Gly vary in different ethnicity population." (PMID 32316934, 2020). "We conducted a meta-analysis of family-based association studies (11 for TDT and 5 for HRR) to investigate the putative association of the Ser9Gly SNP in DRD3 with the risk of schizophrenia." (PMID 32316934, 2020). "Several previous meta-analyses have assessed the potential association of DRD3 Ser9Gly with the risk of schizophrenia in case-control studies." (PMID 32316934, 2020). "In another study involving a cohort of 341 patients with schizophrenia, DRD3 polymorphism (rs1025398) showed an association with the quantity of tobacco smoked (p = 0.002)." (PMID 33287325, 2020). "We decided to investigate the association of rs4680 COMT, rs6280 DRD3, and rs7322347 5HT2A with youth-onset schizophrenia in a homogenous Russian population, because of their prominence in the literature." (PMID 31798476, 2019). "We investigated the associations of rs4680 COMT, rs6280 DRD3, and rs7322347 5HT2A with youth-onset schizophrenia in the Russian population in a case–control study, and the role of the genotype in the severity of clinical features." (PMID 31798476, 2019). "to estimate the prevalence of TaqIA, -141C and rs6280 polymorphisms of theANKK1, DRD2 and DRD3 genes and evaluate their association with theoccurrence of metabolic syndrome in patients with refractory schizophrenia." (PMID 29791666, 2018). "We found significantly higher DRD3 gene expression in CD4+ T cells in schizophrenia; and higher DRD3 expression was associated with proportionally reduced counts of activated and memory Treg cells." (PMID 27244229, 2016). "Studies to date have shown that polymorphisms in DRD3 gene have associations with schizophrenia, depression, nicotine dependence, and attention deficit-hyperactivity disorder." (PMID 26131011, 2015). "Although more studies are needed to reach a definite conclusion, the increased expression of DRD3 mRNA in the lymphocytes of schizophrenic patients was suggested as a diagnostic marker for schizophrenia." (PMID 26561806, 2015). "Therefore, we carried out a meta-analysis of family-based association studies to better evaluate the relationship between DRD3 Ser9Gly SNP and the risk of schizophrenia." (PMID 32316934, 2020). "HTR2A and DRD3 are listed as risk candidate genes for schizophrenia in ClinVar." (PMID 25522158, 2014). "One of the most studied genes in relation to schizophrenia susceptibility is DRD3." (PMID 20657396, 2010). "Furthermore, DRD3 polymorphisms have been related to diverse clinical responses to olanzapine treatment in patients with schizophrenia, and this relationship might be of relevance to PD patients too." (PMID 35741861, 2022). "Recently, an association study in Mexican schizophrenia patients related the single-nucleotide polymorphism A-241G of the DRD2 gene and the Met/Met allele of COMT and Ser/Gly allele of DRD3 genes with resistance to treatment." (PMID 36979877, 2023).
schizophrenia (continued). "There is relatively little literature on dopamine and immune function in bipolar individuals, but studies examining patients diagnosed with schizophrenia, bipolar, and psychosis showed decreased Drd3 and DAT mRNA in PBLs." (PMID 36757901, 2023). "Amisulpride is a DRD2/DRD3/HTR7 inhibitor that has been widely used in high doses to treat schizophrenia and in low doses for the treatment of depressive disorders." (PMID 37014697, 2023). "We investigated the associations of DRD3 rs6280, HTR1A rs6295, BDNF rs6265, SCL6A4 rs16965628, and 5HT2A rs7322347 with schizophrenia in a case–control study, and associations of these genetic variants with several clinical features." (PMID 34025476, 2021). "In fact, HERV-W/MSRV induces activation of the Brain-derived neurotrophic factor (BDNF) and Dopamine receptor D3 (DRD3) genes, both implicated in providing a higher risk for suffering schizophrenia." (PMID 34073730, 2021). "The large sample homogeneous population studies will be necessary to further explore the role of DRD3 in the etiology of schizophrenia." (PMID 32316934, 2020). "Associations between schizophrenia and SNPs in COMT and DRD3 genes are still controversial, there are studies both confirming and refuting these relationships." (PMID 31798476, 2019). "Distribution of DRD3, COMT, and 5HT2A polymorphisms in youth-onset schizophrenia and control groups." (PMID 31798476, 2019). "Role of dopamine D3 receptor (DRD3) and dopamine transporter (DAT) polymorphism in cognitive dysfunctions and therapeutic response to atypical antipsychotics in patients with schizophrenia." (PMID 30093869, 2018). "The changes in lymphocyte DRD3 and DRD5 mRNA seem to be associated with schizophrenia symptom severity, with increased levels observed following antipsychotic treatment." (PMID 28358316, 2017). "The results regarding DRD3 were also conflicting, demonstrating increased, as well as decreased levels of lymphocyte DRD3 mRNA in schizophrenia." (PMID 28358316, 2017). "Further, DRD3 expression correlated with the excitement factor on the PANSS in patients with schizophrenia/schizophreniform disorder." (PMID 27795960, 2016). "The dopamine D 3 receptor gene (DRD3) is candidate for a number of psychiatric conditions including schizophrenia, bipolar disorder, and alcohol and drug abuse." (PMID 26131011, 2015). "DRD3 has been a longstanding candidate gene for schizophrenia, largely based on its affinity to bind antipsychotic drugs and its localization in limbic brain structures." (PMID 24650298, 2014). "The classification models obtained for the evaluated schizophrenia patients using the SNP information at DRD3 and HTR2A." (PMID 20657396, 2010). "More specifically, SNP T102C (rs6313) at HTR2A and SNP Ser9Gly (rs6280) at DRD3 have been extensively analyzed in several schizophrenia case-control studies." (PMID 20657396, 2010). "Meta-analyses of case control studies with DRD2 S311C provides strong evidence that Cys311 allele of DRD2 influences susceptibility to schizophrenia and that the risk associated with this polymorphism is actually greater than either HTR2A or DRD3." (PMID 17651483, 2007). "We once reported that HERV-W ENV increases DRD3, a critical DA receptor involved in schizophrenia." (PMID 35062349, 2022). "Interestingly, DRD3 is one of the primary targets for antipsychotics in treating psychotic symptoms in schizophrenia or other neurological disorders." (PMID 32273551, 2020). "Subsequently, the increasing DRD3-dependant dopamine intracellular signaling may induce the occurrence of schizophrenia." (PMID 32316934, 2020). "The DRD3 gene is considered a candidate gene for schizophrenia: in patients with this disease, an increase in the density of DRD3 in the striatum region has been found, together with a relative accumulation of “truncated forms” of receptor protein formed during abnormal splicing." (PMID 31798476, 2019).
schizophrenia (continued). "Although we did not identify a diagnostic difference in DRD3 or DRD3nf mRNA, schizophrenia cases exhibiting more positive symptoms had a 56% increase in DRD3 mRNA compared with those with more negative symptoms." (PMID 28094812, 2017). "Dopamine receptor D2 short, vesicular monoamine transporter (VMAT2) and DAT mRNAs were significantly decreased in schizophrenia, with no change in DRD3 mRNA, DRD3nf mRNA and DAT protein between diagnostic groups." (PMID 28094812, 2017). "Urhan-Kucuk and colleagues studied 55 schizophrenia patients and 51 healthy subjects to determine whether DRD3 expression in peripheral blood lymphocytes could be used as a marker of disease." (PMID 27795960, 2016). "In particular, the DRD3 Ser-9 allele has been associated with higher risk for schizophrenia, although there is also evidence not confirming this hypothesis." (PMID 35741861, 2022). "Thus, increased DRD3 mRNA and possibly protein may also contribute to dopamine dysregulation in some people with schizophrenia." (PMID 28094812, 2017). "Additionally, it has been suggested that polymorphisms in ADRA2A (alpha-2A adrenergic receptor), DRD3 (dopamine receptor D3), DBH (dopamine β-hydroxylase) and SNAP-25 (25 kDa synaptosomal-associated protein) are individually or collectively risk factors for schizophrenia." (PMID 25408901, 2013). "Thus, it may be particularly relevant to schizophrenia, as the DRD3 messenger RNA is predominantly expressed in the limbic system, a region thought to be dysfunctional in this disease." (PMID 20657396, 2010). "The aim of this study was to research the associations between symptomatology and SNP of genes related to the systems of neurotransmission (DRD3 rs6280, HTR1A rs6295, 5HT2A rs7322347) and neurotrophic factor (BDNF rs6265) in schizophrenia patients." (PMID 34025476, 2021). "Genotype frequencies of rs6280 (DRD3), rs4680 (COMT), and rs7322347 (5HT2A) in the control and youth-onset schizophrenia groups." (PMID 31798476, 2019). "Candidate gene studies have often been focused on the role of dopamine receptors and related genes (namely DRD1, DRD2, DRD3, DRD4, and DRD5) as modulators of antipsychotic drug responsiveness and schizophrenia symptoms." (PMID 30687136, 2018). "Spearman rank correlations analysis between DRD2, DRD3, and DARPP-32 mRNA levels and five factors of the PANSS in patients with psychotic disorder NOS and the schizophrenia/schizophreniform disorder group." (PMID 26561806, 2015). "The expression levels of DRD3 mRNA in T lymphocytes were significantly different among controls and patients with psychotic disorder NOS and schizophrenia/schizophreniform disorder." (PMID 26561806, 2015). "This CREB-dependent mechanism may synergize with GSK3β-mediated pathways, as HERV-W env also enhances CREB phosphorylation to upregulate BDNF and dopamine receptor D3 (DRD3), contributing to excitatory-inhibitory imbalances in schizophrenia." (PMID 41200560, 2025). "In this work, we analyzed 28 studies conducted from 1989 to 2021, studying 37 genetic variations, including SNVs/polymorphisms of four candidate dopamine receptor genes (DRD1, DRD2, DRD3, DRD4) involved in the development of AIP and AITD in patients with schizophrenia." (PMID 34440083, 2021). "There was also no statistical difference between the DRD3:DRD3nf ratio between control and schizophrenia cases (0.88±0.05 and 0.938±0.10; t=0,568, df=52, P=0.572)." (PMID 28094812, 2017). "Schizophrenia subjects exhibited thousands of neuronal and non-neuronal epigenetic differences at regions that included several susceptibility genetic loci, such as NRG1, DISC1, and DRD3." (PMID 38648100, 2024). "More recent work has confirmed such epistatic gene-gene interactions, for instance, by showing that COMT and DRD3 together modulate behavior in children with ADHD and that DRD4 in combination with COMT modulate the clinical responses to clozapine in schizophrenia patients." (PMID 33328916, 2020).
schizophrenia (continued). "Although DRD3 was decreased by 26.76% and DRD3nf was decreased by 23.20% in substantia nigra of people with schizophrenia compared with controls, neither decrease reached statistical significance (F=1.471, df=53, P=0.231 and F=0.949, df=55, P=0.334, respectively)." (PMID 28094812, 2017). "When schizophrenia cases displaying mostly positive or negative symptoms were compared, there was a significant 56.5% increase in DRD3 mRNA in the primarily positive symptoms group compared with those people with schizophrenia displaying mostly negative symptoms (t=−2.188, df=20, P=0.041)." (PMID 28094812, 2017). "The present study demonstrated that the mRNA expression levels of DRD3 in T lymphocytes were significantly different among controls, and in patients with psychotic disorder not otherwise specified (NOS) and schizophrenia/schizophreniform disorder." (PMID 26561806, 2015).